RN7SL228P (RNA, 7SL, cytoplasmic 228, pseudogene)
Gene: Miscellaneous RNA gene on chromosome 8 (117,017,946 to 117,018,248, forward strand). Ensembl gene ENSG00000244033.
Homologues: Orthologues: chimpanzee Metazoa_SRP (99% identical), macaque Metazoa_SRP (95% identical). Paralogues in human: RN7SL2 (81% identical), RN7SL1 (80% identical), RN7SL3 (80% identical), RN7SL321P (80% identical), RN7SL45P (80% identical), RN7SL375P (79% identical), RN7SL597P (78% identical), RN7SL357P (78% identical), RN7SL575P (78% identical), RN7SL126P (78% identical), RN7SL218P (78% identical), RN7SL326P (78% identical), and 702 more.